TGFB1 (transforming growth factor beta 1)
Diseases named in the same sentence as TGFB1 in open-access papers (continued):
Sharing a sentence is not in itself a finding about the gene and the disease.
pancreatic cancer (continued). "Therefore, TIPE2 possibly suppressed the growth of pancreatic cancer through inhibiting TGFβ1 expression." (PMID 34249724, 2021). "These included upregulation SERPINB2, a known oncogene, and a decrease in TGFβ1 expression, a cytokine which may function under specific circumstances as a tumor suppressor in pancreatic cancer." (PMID 32513126, 2020). "As TGFβ1 may play suppressive role in pancreatic cancer development, inhibition of this pathway, may be a possible mechanism by which R269C-ER mediates aggressive behavior of pancreatic cancer cells." (PMID 32513126, 2020). "Therefore, we proposed that pancreatic cancer-derived EVs inhibit NK cell function via the TGFβ1-Smad2/3 pathway." (PMID 31234517, 2019). "Moreover, Dec1 knockdown by small interfering RNA (siRNA) decreased pSmad3 induced by TGFβ1 in pancreatic cancer cells." (PMID 31597354, 2019). "Consistent with our in vitro observations, TGFβ1 expression was elevated in PEDF-deficient samples, and significantly (p<0.001) lower in PEDF-expressing samples, further suggesting that PEDF suppresses TGFβ-mediated fibrosis in pancreatic cancer." (PMID 27058416, 2016). "In conclusion, we provide herein for the first time, solid evidence of a novel anti-NRP-1 therapy that could lead to a reduction in pancreatic tumor fibrosis and growth via a regulatory effect on TGFβ1-induced EndMT." (PMID 27542226, 2016). "Given the adverse outcomes observed following direct targeting of TGFβ1 in pancreatic cancer patients, we explored whether other cytokines downstream of TGFβ1, which may be more favorable therapeutic targets, were implicated in the EMT-associated changes in morphology that we observed." (PMID 36828915, 2023). "Finally, pancreatic cancer cells were stimulated with TGFB1 and ATP11A expression was examined to explore whether the effect of ATP11A on EMT was TGFB dependent." (PMID 35345586, 2022). "In addition, when stimulated with TGFβ1, phenotypic changes in pancreatic cancer cells were inconspicuous, and control cells were more likely to acquire the fibroblast-like shape characteristic of cells undergoing EMT, lose intercellular contacts, and become more isolated from each other." (PMID 34503200, 2021). "Therefore, TIPE2 might exert an anti-tumor effect by activation T cells through DCs in a TGFβ1 dependent manner in pancreatic cancer." (PMID 34249724, 2021). "Notably, if cancer tissues retain the tumour-suppressive responsiveness to TGFβ1, then the blockade of αvβ6 could potentially promote cancer, as was described in a transgenic mouse model of pancreatic cancer." (PMID 27515461, 2016). "The aim of the present study was to improve our understanding of the way in which EGF governs the pancreatic cancer cell response to relevant stromal derived molecules, TGFβ1 and S100A8/A9, while also investigating whether SMAD4 participates in this complex scenario." (PMID 27655713, 2016). "Another study introduces self-activating CAR-NK cells that block TGFβ1 signalling in the TME using a peptide called P6, which targets mesothelin in pancreatic tumours." (PMID 40650066, 2025). "Survival analyses of the MI genes were performed to compare the control and TGFB1 +GEM-treated cells, examining their biological relevance in pancreatic cancer." (PMID 41209344, 2025). "Lastly, TAMs can stimulate PSC proliferation and ECM secretion via TGFβ1 and PDGF respectively, involved in multiple steps of pancreatic cancer progression." (PMID 39195299, 2024). "Further, TGFβ1 was recently shown to induce a novel complex composed of NFAT5, Smad3, and Smad4, which promotes epithelial-to-mesenchymal transition in pancreatic cancer cells." (PMID 39595620, 2024). "In the pancreatic cancer cell line PANC1, JUNB and four of the other eight genes analyzed showed a positive TGFβ1 response." (PMID 36672507, 2023).
pancreatic cancer (continued). "Overexpression of TIPE2 significantly suppressed the proliferation, metastasis, and promoted apoptosis of pancreatic cancer possibly through inhibition of PI3K/AKT and Raf/MEK/ERK signaling pathways triggered by TGFβ1." (PMID 34249724, 2021). "TGFβ1 and S100A8/A9, which share their overall effects on pancreatic cancer cells, mainly inhibit NF-κB and PI3K/AKT in a SMAD4-dependent manner." (PMID 27655713, 2016). "Many more recent studies have shown that TGFβ1 and EGFR inhibitors are promising for the treatment of pancreatic cancer." (PMID 24625091, 2014). "It is clear that TGFβ1 is an important regulator of metastasis and survival in SPARC−/− mice bearing orthotopic pancreatic tumors." (PMID 22348081, 2012). "Additionally, CTNNB1 had the highest deep deletion rate across pan-cancer at 5%, followed by TGFB1 at 3.6% in head and neck cancer and 2.2% in non-small cell lung cancer, and TNF and PPARG in pancreatic cancer with rates of 3.6% and 1.3%, respectively." (PMID 37033970, 2023). "Additionally, TGFβ1 perfusion raised Ca2+ release from the endoplasmic reticulum and so the SOCE in pancreatic cancer cells, suggesting its crucial involvement in pancreatic cancer as well." (PMID 34063470, 2021). "As reported, TGFβ1 is a dual character cytokine during tumorigenesis, and considered to contribute tumor progression by inducing EMT, promoting tumor immune evasion and resisting apoptosis in pancreatic cancer." (PMID 34249724, 2021). "Mechanistic studies exhibited that TIPE2 might suppress pancreatic cancer development through inhibiting PI3K/AKT and Raf/MEK/ERK signaling pathways triggered by TGFβ1." (PMID 34249724, 2021). "Gemcitabine regulates the immune system in patients with pancreatic cancer including MDSCs, Tregs and molecules such as TGFβ-1 but does not hamper the ability of effector lymphocytes to expand to stimuli." (PMID 27687804, 2016). "We investigated whether chronic exposure to EGF modifies in a SMAD4-dependent manner pancreatic cancer cell signalling, proliferation and invasion in response to EGF, TGFβ1 and S100A8/A9." (PMID 27655713, 2016). "Furthermore, TIPE2 could not only inhibit the secretion of TGFβ1, but also decrease the phosphorylation of TGFBR1 in pancreatic cancer cells." (PMID 34249724, 2021). "Similarly, TIPE2 overexpression could decrease the protein level of TGFβ1 and phosphorylation of TGFBR1 in pancreatic cancer." (PMID 34249724, 2021). "Indeed, we found that blocking TGFβ1 with anti-TGFβ1 antibody could reduce the phosphorylation of ERK and AKT in pancreatic cancer, while treating with TGFβ1 protein showed the opposed effect." (PMID 34249724, 2021). "Moreover, TGFβ1 expression was increased in PEDF samples and was statistically significantly lower in PEDF-samples, which may indicate that PEDF is involved in the inhibition of fibrosis in pancreatic cancer via TGFβ1." (PMID 39457573, 2024). "Furthermore, several investigations reported that transforming growth factor-beta 1 (TGF-β1), produced in the tumor microenvironment, could be a strong mediator of pancreatic cancer cell invasion, metastasis, and angiogenesis by upregulating VEGF, MMP-2, and uPA secretion." (PMID 25295247, 2014). "The proliferation of the four studied pancreatic cancer cell lines was not influenced by S100A8, S100A9, S100A8/A9 and/or TGFβ1." (PMID 24670043, 2014).
glioma (757 papers, 1994 to 2026). A benign or malignant brain and spinal cord tumor that arises from glial cells (astrocytes, oligodendrocytes, ependymal cells). "The decision tree analysis indicates that serums ANGPT1, TIMP1, IP10, and TGFβ1 are promising combinations of targets for glioma diagnostic applications." (PMID 31861636, 2019). "FN1, a downstream target and regulator of TGFB1, which plays a key role in matrix assembly was recently associated with glioma cell cohesion and motility, as well as tumour angiogenesis." (PMID 27049916, 2016). "Finally, we discussed the sensitivity of TGFB1 inhibitors in gliomas using cell line susceptibility data." (PMID 36778912, 2022). "Tumor-produced TGFβ1 isoform may be associated with Treg cell infiltration in glioma tissues, and high levels are indicative of a poor prognosis." (PMID 35454784, 2022). "TGFβ1 expression was only slightly upregulated in high-grade gliomas and linked to survival." (PMID 30850588, 2019). "It was previously found that overexpression of SUMO, which occurs in conditions such as brain ischemia and hypoxia, could increase cell survival, whereas in contrast, the knockdown of SUMO expression has been shown to be toxic to cells and is associated with TGFβ1 in resistant glioma cells." (PMID 35582224, 2020). "It has also been extensively studied in gliomas, yet the specific interactions between TGFβ1, TGFβ2, and TGFβ3 isoforms in astrocytic tumors remain poorly understood." (PMID 40620718, 2025). "Other notable signals included IL6, VEGFA, TGFB1, and ANXA1, genes associated with mesenchymal transition, angiogenic niches, and poor prognosis in glioma." (PMID 41514565, 2025). "A previous work has shown that in gliomas, regulatory T cells secrete TGFB1 and thereby promote the NF-kB-IL6-STAT3 signaling axis, and IL6 receptor blockers have a potential therapeutic effect." (PMID 38981682, 2024). "The survival rates of the cases with high-grade glial tumors were evaluated with respect to TGFB1-509C/T genotypes." (PMID 38256406, 2024). "Subsequently, we further analyzed the previous transcriptome sequencing data and found that silencing PRMT6 in glioma cells can reduce the expression of invasion-related molecules (TGFB1/2, MMP3/9/14, FN1, ROCK2, etc.)." (PMID 39043634, 2024). "It is likely that microglia-derived TGFβ1 also contributes to canine glioma cell malignancy, as our laboratory observed robust TGFβ1 immunoreactivity (IR) at the leading edge of the tumor mass corresponding with increased GAM density in canine astrocytoma." (PMID 37368789, 2023). "In particular, microglia-derived TGFβ1 stimulated glioma cell invasion into surrounding normal brain parenchyma in rodent models and human glioma." (PMID 37368789, 2023). "FGL2, IL10, TGFB1, and VEGFA were secreted immunosuppressive molecules in glioma and were consistently upregulated in high-risk group from all four datasets." (PMID 37864127, 2023). "Increased TGFβ1 expression was observed in the majority of glioma samples and correlated with a high grade, which is consistent with the results obtained in our work." (PMID 35454784, 2022). "From these analyses, we demonstrated a viable clinical strategy in combination with TGFB1/TGFBR1 inhibitors and PD-1/PD-L1 inhibitors for the treatment of high-risk gliomas." (PMID 36778912, 2022). "In gliomas, TGFβ1 stimulation has been related to increased glucose uptake, glycolytic flux, and lactate production mediated, at least in part, by an increment in GLUT1 expression." (PMID 35574033, 2022). "Functionally, GDEs and miR-3591-3p significantly induced M2 macrophage polarization and increased the secretion of IL10 and TGFβ1, which in turn promoted glioma invasion and migration." (PMID 36085418, 2022). "An analysis of the differentiation of the normalized values of fluorescent signals showed that the expression levels of TGFβ1 and TGFβ2 were statistically significantly changed in gliomas of different stages." (PMID 35454784, 2022).
glioma (continued). "Their study demonstrated that CCR7 mediates TGFB1-induced migration of glioma cells through the activation of matrix metalloproteinase 2 (MMP2)/9." (PMID 34643804, 2022). "The Spearman correlation analysis results suggested that the immune marker sets of Treg (FOXP3, CCR8, TGFβ1), TAM (CCL2, CD68, IL-10), and MDSC (CD33, ITGAM, FUT4) were significantly associated with the PROS1 expression in glioma." (PMID 36685506, 2022). "By exploring the relationship between the FDX1 gene and immune checkpoint genes, we found that there is a strong co-expression relationship between the FDX1 gene and immune checkpoint Suppressor gene TGFB1 in glioma." (PMID 36523779, 2022). "TGFβ1 is overexpressed in gliomas and plays important roles in glioma proliferation, invasion and immunosuppression." (PMID 34341417, 2021). "While the glioma-microglia signaling axis is complex, transforming growth factor beta 1 (TGFB1) has been identified as a key mediator of glioma progression." (PMID 34131649, 2021). "Intriguingly, TGFβ1 secreted by TAMs also increased expression of MMP9 in glioma stem-like cells that contributes to the invasive ability of these cancer stem cells." (PMID 32283687, 2020). "Of note, TAMs that express high levels of TGFβ1 were at the invasive front of CD133+ glioma stem-like cells, which are responsible for glioma invasion." (PMID 32283687, 2020). "Another study identified SMAD7 as a target of miR-195 in glioma and showed that TGFβ1 promotes miR-195 expression, inhibits SMAD7 expression, and promotes U87 cell proliferation and invasion." (PMID 33085646, 2020). "Next, the expression of BACE2 was upregulated with increasing concentrations of TGFβ1 in the medium for both glioma cell lines." (PMID 31856384, 2020). "OKN-007 treated F98 gliomas had substantially decreased TGFB1 protein levels, resulting in TGFB1 inhibition as the upstream regulator, and 57 downregulated genes within this pathway." (PMID 33168005, 2020). "Given that CD86, LGALS9, and TGFB1 play immunosuppressive roles in glioma, we further investigated the expressing relationship between C1RL and these immunosuppressive genes." (PMID 32993564, 2020). "We investigated the role of transforming growth factor beta 1 (TGF-beta 1) in the control of proliferation of human glioma cell lines as well as normal human fetal brain cells." (PMID 8054266, 1994). "Thus, by competing with miR-133b-3p, HOTAIRM1 increased TGFB1 expression and TGF-β signaling in gliomas." (PMID 38571882, 2024). "Additionally, MSCs-EVs delivered miR-744-5p to block glioma progression by inhibiting macrophage TGFB1 expression and M2 polarization via miR-744-5p/TGFB1/MAPK axis." (PMID 39372421, 2024). "In the cancer-immunity cycle, we found genes that inhibit the cycle, including the glioma-secreted and cell-surface immunosuppressive factors, TGFB1, VEGFA, ARG1, IL10, and CD70, they were highly expressed in the high-risk group and were positively correlated with the risk score." (PMID 37891828, 2023). "The G34-mutated tumors have been found to rely on the TGFB1 and HAVCR2 (TIM3) pathways for immune evasion indicating that the underlying genetic makeup of the glioma may influence preferential dominant immune-suppressive mechanisms." (PMID 37509316, 2023). "Third, glioma cells have permanent expression of the immunosuppressive molecules TGFβ1 and TGFβ2." (PMID 38168422, 2023). "By analyzing the main signaling pathways that induce the EMT phenotype, we found that TGF-β was the most important one in gliomas, and TGFB1/TGFBR1 showed stronger immunosuppressive properties than PD-L1 and CTLA-4, especially in inducing an increase in CD8+ T cytopenia and M2 macrophages." (PMID 36778912, 2022). "Finally, we explored the relative drug sensitivity of the TGFB1 inhibitor in glioma cell lines through the Genomics of Drug Sensitivity in Cancer website and the EMTome website." (PMID 36778912, 2022).
glioma (continued). "In this trial, TGFB1 and IL-8 mRNA positively correlated with the immunologic responses to glioma antigens in the EVs isolated from the post-vaccine group, suggesting the potential of mRNAs carried by EVs to assess the response of vaccination therapy in glioma patients." (PMID 35493080, 2022). "Increased TGFB1 IR at the leading edge of the tumor mass led us to hypothesize that TGFB1 directly contributes to canine glioma invasion." (PMID 34131649, 2021). "Moreover, TGFβ1 induces the expression of integrins that directly promote the capacity of glioma cells to migrate." (PMID 34012965, 2021). "In low-grade glioma, the expression level of transforming growth factor beta 1 (TGF-β) and programmed cell death ligand 1 (PDL1) was positively correlated with immune risk score, and prognostic hub genes that were positively correlated with immune cell infiltration have also been revealed." (PMID 34539626, 2021). "It was reported that SD‐208, a TGFB1 inhibitor, could enhance the immunogenicity and inhibit the growth and invasiveness of murine and human glioma cells." (PMID 33987093, 2021). "Moreover, the mature TGFB1 isoform (44 kD) was increased 3.5-fold in high-grade astrocytoma relative to normal brain (**P < .01) and low-grade glioma (*P < .05)." (PMID 34131649, 2021). "CD86, LGALS9, and TGFB1 play immunosuppressive roles in glioma." (PMID 32993564, 2020). "However, further research should be undertaken to investigate the potential molecular mechanisms that coordinate BACE2 and TGFβ1 signalling in gliomas." (PMID 31856384, 2020). "In addition, PFKFB3 was also upregulated by TGFβ1 in glioma cells, resulting in an increase in fructose 2,6-bisphosphate, glucose uptake, glycolytic flux and lactate production." (PMID 31822964, 2020). "In the in vitro experiments, TGFβ1 induced BACE2 expression in two glioma cell lines." (PMID 31856384, 2020). "Furthermore, the TCGA and CCLE data showed that STC1, HMOX1 and TGFB1 were obviously up‐regulated in most glioma cells." (PMID 31282108, 2019). "We demonstrate that by using low‐dose anti‐VEGFR and anti‐TGFβ1 antibodies, we could normalize blood vessels and decrease collagen content within murine syngeneic gliomas." (PMID 30886813, 2019). "In addition to these, MAPKAPK2 is positively correlated with IL6, IL6R, IL10, IL10RB, TGFβ1, etc., in the present study, which may facilitate the glioma progression." (PMID 38322416, 2024). "Moreover, TGFβ1 increased canine glioma cell migration and invasion in vitro." (PMID 37368789, 2023). "This suggested that TGFB1/TGFBR1 inhibitors may be sensitive in gliomas." (PMID 36778912, 2022). "Subsequently, we further evaluated the representative glioma‐associated microglia/macrophage (GAM)‐related genes expression level between high‐ and low‐risk group, higher expression level of IBA1, TMEM119, CD68, CSF1R, and TGFB1 was found in the high‐risk group." (PMID 35985661, 2022). "Moreover, there was a correlation between BACE2 and TGFβ1 expression in glioma patients." (PMID 31856384, 2020). "However, the regulation mechanism of CEBPB on TGFB1/SMAD3 in glioma was seldom studied." (PMID 27716259, 2016). "For instance, in mouse xenograft models of human glioma, high POSTN mediated enhanced expression of TGFB1 and HIF1 alpha, which resulted in acquired resistance to anti-VEGF-A therapy." (PMID 38942020, 2024). "TGFB1 and TGFB2 have been identified as the most highly expressed tumor-promoting cytokine in the TME of gliomas, prompting us to characterize the abundance of TGFB1 and TGFB2 mRNA addition to the upregulation of TAM cell surface markers." (PMID 38539537, 2024). "Overexpression of systemic immunosuppressive soluble factors by glioma cells, such as PTGS2 (rate-limiting step catalyzed by COX-2), TGFB1, IDO1, and IL-10, were also investigated at the transcriptional level." (PMID 37322408, 2023).